ATF4 (activating transcription factor 4)
Diseases named in the same sentence as ATF4 in open-access papers (continued):
Sharing a sentence is not in itself a finding about the gene and the disease.
tumor (continued). "Once induced, ATF4 coordinates transcriptional programs that regulate amino acid metabolism, cellular redox homeostasis, and the unfolded protein response (UPR), enabling tumor cells to cope with metabolic stress." (PMID 40951358, 2025). "Meanwhile, ATF4, a transcription factor in the unfolded protein response (UPR), has been shown to be essential for PCa growth, with increased expression in tumors and a critical role in maintaining tumor survival through its downstream effector FAM129A." (PMID 41440174, 2025). "Although ATF4 plays negative and positive roles within the tumor microenvironment, we investigated the effect of its upregulation in T cells in the context of amino acid scarcity." (PMID 40335738, 2025). "Activating transcription factor 4 (ATF4) and N-Myc cooperatively bind to the ASCT2 promoter, enhancing its transcriptional activity and thereby increasing glutamine uptake to supply energy and carbon sources for tumor cells." (PMID 41278473, 2025). "In contrast, tumour cells take advantage of stress-related transcription factors, including nuclear factor erythroid 2-related factor 2 (NRF2) and activating transcription factor 4 (ATF4), to increase SLC7A11 expression to combat ferroptosis." (PMID 38993573, 2024). "In summary, our work indicates that DT-061, and potentially other chemical modulators of PP2A, regulate an alternative cellular stress response pathway, activating an irreversible ATF4-CHOP pro-death response in tumor cells but not in normal cells." (PMID 39349971, 2024). "The concurrent activation of ISR (ATF4 signature) and OSR (NRF2 signature) in the liver suggests potential synergy, a phenomenon previously observed in cell lines and tumor models." (PMID 39131293, 2024). "Furtherly, in vivo results shown that ATF4‐OE group displayed larger tumour volumes than the EV group, while DHA treatment could inhibit the tumour growth and proliferation effectively." (PMID 38652216, 2024). "These surviving tumor cells acquire enhanced tumorigenic and metastatic capabilities by activating ATF4‐dependent nonclassical NF‐κB signaling pathway, which provides a new mechanistic explanation for chemotherapy‐induced tumor metastasis." (PMID 36739602, 2023). "Activating transcription factor 4 (ATF4) is a critical oxido-metabolic regulator that contributes to the malignancy of HGGs by promoting cell proliferation, migration and tumor angiogenesis through the modification of the microenvironment in a potentially harmful way." (PMID 37554158, 2023). "ATF4 regulates tumor autophagy in CRC and affects tumor survival." (PMID 36299603, 2022). "By contrast, treatments by GSK621 which could activate ATF4 or by CeapinA7, an ATF6 inhibitor, significantly suppressed tumor metastasis rates." (PMID 35883579, 2022). "Similarly, targeting of the PERK‐eIF2a‐ATF4 branch of the UPR effectively reduces tumour progression and metastasis dissemination in preclinical models of CRPC, while ATF4 signalling is essential for PCa growth and survival." (PMID 35014179, 2022). "A recent report demonstrated enhanced combinatorial anti-tumor activity of ETC inhibition with dietary asparagine restriction with asparaginase, through depletion of exogenous asparagine that communicates active respiration to ATF4 and mTORC154." (PMID 35589701, 2022). "In addition, it has been shown that tumor growth is heavily dependent on glutamine and that glutamine deprivation increases DDIT3 expression through activating transcription factor-4 (ATF4)-mediated transcription." (PMID 36233241, 2022).
tumor (continued). "A limited number of studies have investigated the role of p19Arf in the context of the ISR pathway, with one study showing that deletion of the ISR-regulated gene ATF4 increased the expression of the CDKN2A genes p16Ink4a and p19Arf suppressing colony formation and tumor growth." (PMID 34994382, 2022). "Previous studies have demonstrated that transcriptional and post‐transcriptional suppression of SLC7A11 by transcription factors (such as ATF3 and ATF4), H2A deubiquitinases (such as BAP1), and epigenetic modifications (such as H2Bub1) can promote erastin‐induced tumour cell ferroptosis." (PMID 35522946, 2022). "However, ATF4, a pro‐survival effector of the ISR arm of UPR (downstream to the PERK branch), is down‐regulated in the treated ERO1 KO tumours compared with the WT counterparts." (PMID 35853086, 2022). "In different two-dimensional (2D) tumor cell systems, sustained ER stress by misfolded or unfolded protein accumulation in the ER induces the PERK/ATF4/CHOP/TRAIL-R2/DR5-dependent and TRAIL-independent intracellular DISC assembly that activates a caspase-8-mediated apoptotic pathway." (PMID 35115486, 2022). "Interestingly, amino acid deprivation-induced VEGF expression is evident in human tumors and tumor cell lines, suggesting that the EIF2AK4/ATF4 axis stimulates tumor angiogenesis." (PMID 36293401, 2022). "However, sustained ATF4 production often leads to induction of the pro-apoptotic gene for CHOP, which in turn would promote apoptosis and programmed tumor cell death." (PMID 34914716, 2021). "LC3B-II and ATF4 protein were increased in the muscle of KPC but not KPC IL6KO tumor–bearing mice, while Beclin-1 was unchanged in muscle of mice with KPC tumors and actually decreased in muscle of mice with KPC IL6KO tumors." (PMID 33851955, 2021). "Moreover, statistical analysis demonstrated that the ATF4 expression level in PDAC patients was correlated with differentiation, tumor stage, and neural invasion." (PMID 33782384, 2021). "Immunohistochemistry analysis of these tumours revealed that feeding mice with a -SG diet led to a clear induction of PSAT1 – and to a lesser extent PHGDH – in tumours, indicating the induction of an ATF-4 response in vivo." (PMID 33446657, 2021). "To further investigate whether ATF4 played a role in tumor growth in vivo, we performed a subcutaneous injection of PANC-1 cells with stable ATF4 knockdown (PANC-1 shATF4) or mock-transfected cells (shNC) into the bilateral hind legs of athymic nude mice." (PMID 33782384, 2021). "Arguably, the GCN2‐eIF2α‐ATF4 pathway, which is critical for maintaining metabolic homeostasis in tumor cells, is apparently not a characteristic of aneuploid cells." (PMID 34698427, 2021). "In GB ATF4 has not yet been studied in the context of hypoxia and combined glucose deprivation which characterize the conditions of the tumor microenvironment." (PMID 34239013, 2021). "Similarly, in glioma cells, ATF4 gene knockout increases the sensitivity of tumor cells to RSL3- and erastin-induced ferroptosis to inhibit tumor growth." (PMID 33980834, 2021). "(A) mRNA expression of ER-stress markers Edem1, Ero1b, Grp94, Herp, Atf4, Eif2ak3, Ddit3, and Hspa5 in liver tissue from healthy mice; and tumor tissue and surrounding non-tumoral tissue from mice with DEN-induced HCC." (PMID 33103995, 2020). "Taken together, ER stress may upregulate GOLGA2P10 through the PERK/ATF4/CHOP pathway, and the elevated GOLGA2P10 may confer tumor cells with resistance to ER stress-induced apoptosis by increasing the protein level of BCL-xL and the phosphorylation of BAD." (PMID 32332695, 2020). "Consistently, the administration of (−)-agelamide D alone did not affect xenograft tumor growth in nude mice but enhanced tumor growth inhibition in combination with RT, which correlated with an increase in ATF4 expression and apoptotic cells within tumors." (PMID 33003597, 2020).
tumor (continued). "To determine whether the activation of the PERK/ eIF2α/ATF4/CHOP signaling pathway and inactivation of the AKT/mTOR signaling pathway were involved in CCT020312-induced tumor inhibition, we performed western blotting and IHC." (PMID 32508655, 2020). "Under this condition, the phosphorylation of eukaryotic initiation factor 2α (eIF2 α) occurs by activation of GCN2, which upregulates activating transcription factor 4 (ATF4) expression, increases amino acid biosynthesis, and eventually induces tumor immunoresistance and its survival." (PMID 33330446, 2020). "The fact that overexpression of ATF4 aggravates malignant phenotypes has also been confirmed in the case of high-grade gliomas (HGG), wherein it evokes increased proliferation, angiogenesis, and tumor cell migration." (PMID 31491919, 2019). "On the contrary, it was also found that the knockdown of ATF4 in two endometrial cancer (EC) cell lines suppressed tumor growth in vivo but had no impact on cell proliferation in vitro." (PMID 31491919, 2019). "In addition, continuous oral feeding of mice with fucoidan significantly prevents tumorigenesis and reduces tumor size in an LLC1-bearing mouse model and induces ATF4 and CHOP protein expression in mice in vivo." (PMID 31041568, 2019). "In addition, knockdown of the PERK/ATF4/LAMP3 signaling pathway, which is mobilized via radiotherapy, downregulates the DDR and sensitizes tumor cells to radiation." (PMID 31491919, 2019). "SCC had significant correlations between IRF1 and eIF2α or ATF4 in the tumor but not in the normal tissue." (PMID 30305853, 2018). "The results may suggest that the PD1/PDL1 reverse signaling may activate the eIF2α/ATF4 pathway in tumor surrounding cells and IRF1 may be active in regulating PDL1 expression in the tumor tissue." (PMID 30305853, 2018). "Increased ATF4 expression has been detected in some tumors, providing a possible mechanism for coupling malignant transformation to expression of ULBP1, and consequently to tumor immunosurveillance." (PMID 26565589, 2015). "Overall, our data demonstrate that iNOS inhibition could impair EMT and tumor cell migration by impairing ER stress (IRE1α/XBP1) and the crosstalk between ATF4, ATF3, and TGFβ." (PMID 25849745, 2015). "Recently, the expression of ATF4 was found to be elevated in hypoxia-induced circulating tumor cells but not in parental cells." (PMID 25078779, 2014). "Some of these gene nodes have been shown to be functionally involved in other cancer types, including regulation of tumor cell proliferation (Creb, C/ebp, ATF3, ATF4), invasion (MTHFD2, FGF2) and metastasis (PTGS1/COX1, E-selectin, ATF3, FGF2, IL1A, MMP1, MMP13)." (PMID 24124450, 2013). "In support of the hypothesis that ER stress signals can be tumor suppressive, recent findings showed that ATF6, ATF4 and XBP-1 signaling can suppress H-Ras induced transformation in melanocytes." (PMID 17637831, 2007). "Furthermore, a positive correlation between ATF4 and METTL1 was observed in cSCC tumor tissues." (PMID 39870616, 2025). "Although drugs targeting ATF4-Gln axis (e.g., DHA [dihydroartemisinin] inducing ATF4 degradation, SLC1A5 monoclonal antibodies) show efficacy in preclinical studies, they face challenges including metabolic plasticity, tumor heterogeneity, and toxicity to normal tissues." (PMID 40830338, 2025). "However, our in vitro genome‐wide immune screen results showed that knockout of Atf4, Ddit3, Slc7a11, or Slc3a2 alone did not significantly enhance tumor cell sensitivity to T cell–mediated killing." (PMID 41042068, 2025). "COPS5, which is overexpressed in HCC in an amplification‐ and ATF4‐dependent manner, stabilizes MK2 through deubiquitination and, in turn, induces HSPB1 activation, protecting HCC cells from ferroptosis and thus promoting sorafenib resistance and tumor progression." (PMID 40198582, 2025).
tumor (continued). "For instance, ATF4-driven glutathione biosynthesis enhances the capacity of cancer cells to scavenge reactive oxygen species (ROS), thereby promoting redox homeostasis (Activation of LXR β inhibits tumor respiration and is synthetically lethal with Bcl-xL inhibition)." (PMID 40830338, 2025). "Immunohistochemistry and western blotting analyses demonstrated that ATF4 knockdown suppressed the expression of the glutamine transporter alanine, serine, and cysteine‐preferring transporter 2 (ASCT2), thereby affecting glutamine uptake and utilization in tumor cells during glutamine restriction." (PMID 38994891, 2024). "The findings of this study highlight the important role of natural products in activating the tumor immune microenvironment, promoting apoptosis and other forms of cell death, primarily through ROS-induced endoplasmic reticulum stress responses and PERK/eIF2 α/ATF4 signaling pathways." (PMID 39445013, 2024). "Similarly, we detected the JNK pathway and the expression of ATF4 and CHOP in tumor tissues." (PMID 37833257, 2023). "However, the potential roles of the ISR and particularly of ATF4 in host-dependent, tumour-adaptive processes, have not been extensively investigated." (PMID 35654839, 2022). "The ATF4/CHOP axis promotes protein synthesis and subsequently accelerates ROS production, while the treatment of antioxidants and depletion of RPL24 reduces apoptosis by decreasing ROS production and protein synthesis, indicating that PERK is involved in tumor suppression." (PMID 30282948, 2018). "Also, we observed that the feline tumoral cells were more responsive to BB-CLA compared to canine tumoral cells and in parallel, we found that untreated feline cells have inherently more nuclear ATF4 and thus are at a higher baseline ER stress level." (PMID 29649984, 2018). "However, there are various effector genes induced by ATF4, whereas it has not yet elucidated which of them are operational for malignant transformation, tumor progression and therapy resistance." (PMID 28881638, 2017). "Moreover, fostered ATF4 expression increases tumor migration which is almost not affected by TMZ treatment." (PMID 28881638, 2017). "Although these results do not address whether there is a direct role for PERK or ATF4 in compensating for GCN2 loss, we speculate that the development of these alternative signaling mechanisms indicates that the ISR is crucial for tumor cell survival." (PMID 26123823, 2015). "The segregation of the patients into ATF4-positive and -negative groups did not reveal significant correlations with the clinicopathological parameters of age, sex, drinking habit, tumor site, or tumor differentiation." (PMID 25078779, 2014). "Additionally, hypoxia-induced ATF4 has been found in circulating tumor cells (high metastatic potential) but not in their parental cells." (PMID 25078779, 2014). "Our analyses showed that the transcriptome associated with RASSF1, a tumor suppressor involved in cell cycle regulation and not previously linked to UPR, is highly correlated with the transcriptome of several UPR‐related genes, such as BiP/GRP78, DNAJB9, GRP94, ATF4, DNAJC3, and CHOP/DDIT3." (PMID 36723232, 2023). "In addition, tumor cells induce the DNA/RNA helicase Senataxin (SETX) under radiobiological hypoxia, which inhibits cellular apoptosis assisted by the protein kinase R (PKR)-like endoplasmic reticulum kinase (PERK)/activating transcription factor 4 (ATF4) arm of the unfolded protein response (UPR)." (PMID 33796526, 2021). "However, ATF4 overexpression failed to increase the expression level of a series of proangiogenic factors including vascular endothelial growth factor A (VEGFA) in tumor cells in this model." (PMID 25883982, 2015). "NF-κB is a well-known transcription factor that upregulates LCN2 levels in tumor cells under inflammatory conditions and ER stress, but the regulation of LCN2 by ATF4 and STAT3 in tumor biology has not yet been reported." (PMID 40109857, 2025).
tumor (continued). "ATF4, GCN2, and ASNS were expressed at low levels in CC tissues, and all had a significant negative correlation with tumor diameter." (PMID 38844625, 2024). "Our results demonstrate that when tumor cells are grown in the absence of glutamine, stimulation of the GCN2/ATF4/CHOP pathway results in TRAIL-R2 upregulation, an important event leading to caspase-8 activation and apoptosis." (PMID 36302756, 2022). "We note that the relationship between ATF4 and DDIT3, while not consistently perturbed—ATF4 and DDIT3 co‐expression was only significantly perturbed in 5 tumor types (Fig EV4, EV5; UCEC, THYM, THCA, BRCA, and HNSC, respectively)—was also not preserved." (PMID 34698427, 2021). "In tumor cells, the ubiquitin ligase RNF4 ubiquitinates and stabilizes phospho-eIF2α but not ATF4 and CHOP, generating a positive feed-forward loop." (PMID 34106769, 2021). "Notably, in chondrosarcoma, only a single study reports that PRP-1 (proline-rich polypeptide), a toll-like receptor ligand, increases the expression of PERK, eIF2α, ATF4, CHOP, ATF6, IRE1α, and XBP1; however, no studies have yet investigated the functional role of the UPR in this tumor." (PMID 41228282, 2025). "The data suggest that TRIB3 is induced by hypoxia in an ATF4 dependent manner and supports hypoxia sensitivity, but from the measurements of other hypoxia markers we find that TRIB3 mRNA abundance from tumor biopsies is not merely a reflection of tumor hypoxia." (PMID 21864376, 2011).